OIP5 (Opa interacting protein 5)
Diseases named in the same sentence as OIP5 in open-access papers (continued):
Sharing a sentence is not in itself a finding about the gene and the disease.
ovarian carcinoma (1 paper, 2023). A malignant neoplasm originating from the surface ovarian epithelium. "We first analyzed the expression of OIP5 in ovarian cancer and various human tumors with the Sangerbox online analysis tool." (PMID 37660035, 2023). "In short, these results revealed that OIP5 promoted the migration and invasion of ovarian cancer cells, and knockdown of OIP5 markedly suppressed the migratory and invasive abilities of ovarian cancer cells." (PMID 37660035, 2023). "Taken together, these results indicated that downregulation of OIP5 induced cell cycle arrest and apoptosis in ovarian cancer cells." (PMID 37660035, 2023). "In conclusion, these results indicated that knockdown of OIP5 significantly inhibited the proliferation of ovarian cancer cells." (PMID 37660035, 2023). "Cell function assays confirmed that knockdown of OIP5 significantly suppressed the proliferation, migration and invasion of A2780 ovarian cancer cells, apoptosis was increased, and the cell cycle was arrested at the G1/S phase." (PMID 37660035, 2023). "We also analyzed the protein expression of OIP5 in ovarian cancer cell lines using western blotting." (PMID 37660035, 2023). "We found that the expression of OIP5 was significantly upregulated in ovarian cancer tissues compared to normal ovarian tissues." (PMID 37660035, 2023). "Subsequently, we demonstrated that the proliferation and migration of the ovarian cancer cell line A2780 were significantly inhibited after OIP5 gene silencing, apoptosis was increased and cell cycle progression was arrested at the G1 phase." (PMID 37660035, 2023). "The results showed that the protein expression of OIP5 was significantly increased in three ovarian cancer cell lines (SKOV3, A2780, OVCAR-3 cells) compared with IOSE80 cells." (PMID 37660035, 2023). "RT–PCR assays, immunohistochemistry and Western blotting were also used to confirm the high expression of OIP5 in ovarian cancer." (PMID 37660035, 2023). "In summary, these results indicated that OIP5 was highly expressed in ovarian cancer tissues and cell lines." (PMID 37660035, 2023). "The results showed that downregulation of OIP5 resulted in increased apoptosis of A2780 ovarian cancer cells." (PMID 37660035, 2023). "The results showed a significant increase in the mRNA expression level of OIP5 in ovarian cancer compared to normal ovarian tissues." (PMID 37660035, 2023). "The percentage of A2780 ovarian cancer cells in the G1 phase was significantly increased after OIP5 silencing, while the percentage of cells in the S phase and G2/M phase was decreased." (PMID 37660035, 2023). "RT‒PCR was used to analyze the mRNA expression level of OIP5 in ovarian cancer tissues and cell lines." (PMID 37660035, 2023). "The effect of OIP5 on the migration and invasion of ovarian cancer cells was analyzed with Transwell assays." (PMID 37660035, 2023). "Next, a Transwell assay was used to determine the effect of OIP5 on the migration and invasion of A2780 ovarian cancer cells." (PMID 37660035, 2023). "We analyzed the protein expression of OIP5 in ovarian cancer and normal ovarian tissues through immunohistochemistry." (PMID 37660035, 2023). "This study indicated that OIP5 was highly expressed in ovarian cancer and that downregulation of OIP5 inhibited the proliferation, migration and invasion of ovarian cancer cells, induced cell cycle arrest and promoted cell apoptosis." (PMID 37660035, 2023). "Eventually, the ROC curve verified the sensitivity and specificity of OIP5 as a biomarker for the diagnosis of ovarian cancer, with an area under the curve (AUC) equal to 0.984 (CI: 0.975–0.994)." (PMID 37660035, 2023). "The results showed that the migration and invasion of A2780 ovarian cancer cells were significantly decreased after OIP5 silencing." (PMID 37660035, 2023). "In this study, we found that OIP5 is highly expressed in ovarian cancer and is closely related to the cell cycle through bioinformatics analysis." (PMID 37660035, 2023).
ovarian carcinoma (continued). "Next, RT–PCR, immunohistochemistry and Western blotting were utilized to evaluate the expression of OIP5 in ovarian cancer." (PMID 37660035, 2023). "We found that OIP5 is highly expressed in ovarian cancer through bioinformatics analysis, and importantly, OIP5 may be an important biomarker for the prognosis and diagnosis of ovarian cancer." (PMID 37660035, 2023). "High expression of OIP5 was observed in ovarian cancer samples in three datasets." (PMID 37660035, 2023). "In addition, immunohistochemistry, RT‒PCR, and Western blotting were used to further validate the high expression of OIP5 in ovarian cancer." (PMID 37660035, 2023). "Then, we further verified the high expression of OIP5 in ovarian cancer with the GEPIA database." (PMID 37660035, 2023). "In summary, OIP5 was highly expressed in ovarian cancer, and knockdown of OIP5 significantly inhibited the proliferation, migration and invasion of ovarian cancer cells; cell apoptosis increased, and the cell cycle was arrested in the G1/S phase when the OIP5 gene was silenced." (PMID 37660035, 2023). "Moreover, the mRNA expression of OIP5 in ovarian cancer cell lines (SKOV3, A2780, OVCAR-3 cells) was significantly higher than that in the IOSE80 normal ovarian cell line." (PMID 37660035, 2023). "The current research results suggest that OIP5 may be a meaningful biomarker for the early diagnosis and treatment of ovarian cancer." (PMID 37660035, 2023). "However, this study has some limitations that could be addressed by increasing the number of ovarian cancer cell lines and further exploring the mechanism of OIP5 in the carcinogenesis and progression of ovarian cancer." (PMID 37660035, 2023). "Hence,we proposed a scientific hypothesis to determine whether the OIP5 gene can also promote tumor progression and metastasis in ovarian cancer." (PMID 37660035, 2023). "Therefore, OIP5 may be an important biomarker for the early diagnosis and potential target for treatment of ovarian cancer." (PMID 37660035, 2023). "Next, we further investigated the positive correlation between OIP5 and CENPA in ovarian cancer by GEPIA." (PMID 37660035, 2023). "However, the role of OIP5 in the carcinogenesis and progression of ovarian cancer remains unknown." (PMID 37660035, 2023). "However, the role of OIP5 in the carcinogenesis and progression of ovarian cancer has not been investigated." (PMID 37660035, 2023). "However, at present, a detailed understanding of the role of OIP5 in ovarian cancer is lacking." (PMID 37660035, 2023).
primary immunodeficiency (1 paper, 2022). "Moreover, a pathway enrichment analysis of 49 OIP5-associated immunomodulators demonstrated the involvement of the T cell receptor signaling pathway, the JAK-STAT signaling pathway, the NF-kappa B signaling pathway and the primary immunodeficiency pathway." (PMID 35242130, 2022). "The results of KEGG pathways showed that T cell receptor signaling pathway, primary immunodeficiency, Natural killer cell mediated cytotoxicity, NF-kappa B signaling pathway, JAK-STAT signaling pathway and Cytokine-cytokine receptor interaction were related to OIP5-mediated immune events." (PMID 35242130, 2022).
Sertoli Cell-Only Syndrome (1 paper, 2023). A type of male infertility in which no germ cells are visible in any of the biopsied SEMINIFEROUS TUBULES (type I) or in which germ cells are present in a minority of tubules (type II). "Significantly, we have identified a number of variations of OIP5 in NOA patients, and the expression level of OIP5 was significantly lower in NOA patients with spermatocyte maturation arrest, spermatogonial maturation arrest, or Sertoli-cell-only syndrome (SOCS)." (PMID 37292517, 2023).
cancer (28 papers, 2011 to 2025). A tumor composed of atypical neoplastic, often pleomorphic cells that invade other tissues. "OIP5 (Opa-interacting protein 5), involved in centromere function and chromosomal stability, is highly expressed in several cancers including CRC and is associated with cell cycle progression, poor prognosis, and immune evasion." (PMID 40599850, 2025). "OIP5, known for its role in cell cycle regulation, is overexpressed in various cancers and has been associated with poor prognosis in CRC patients." (PMID 40599850, 2025). "OIP5 encodes a protein associated with cancer/testis antigen (CTA) and has been shown to promote oncogenic signaling by interacting with the mTORC1 and β-linked protein pathways." (PMID 38243040, 2024). "Opa interacting protein 5 (OIP5), overexpressed in some types of human cancers, has been reported to be associated with the carcinogenesis of human cancer." (PMID 35242130, 2022). "The upregulation of OIP5 is associated with adverse clinical features in multiple cancer types, including gastric cancer." (PMID 36661650, 2022). "OIP5 (Opa interacting protein 5) is a cancer testis antigen and has been reported in other cancer types as a type of tumor‐associated antigen (TAA); its detection in PC here suggests OIP5 being a TAA for PC." (PMID 30024105, 2018). "In the fission yeast Schizosaccharomyces pombe, overexpression of OIP5 causes multi-septa formation and growth defects, both of which are considered cancer-related phenotypes." (PMID 28184024, 2017). "To date, there are only around 10 reports for OIP5 and most of papers show the association of OIP5 and cancer." (PMID 24516558, 2014). "OIP5 upregulation is observed in human cancers, and seems to be linked to drug resistance." (PMID 35873497, 2022). "Opa interacting protein 5 (OIP5), which is a cancer/testis-specific gene, plays a cancer-promoting role in various types of human cancer." (PMID 37660035, 2023). "OIP5 is a cancer/testis-specific antigen, and it has been reported that OIP5 plays a key role in cell cycle regulation." (PMID 37660035, 2023). "Consistent with the effect of OIP5 on cancer, we have demonstrated that OIP5 knockdown significantly suppressed proliferation and DNA synthesis of human SSCs and increased their apoptosis." (PMID 37292517, 2023). "OIP5-AS1overexpression leads to a decrease in cancer cell survival and enhances the sensitivity to radiotherapy." (PMID 33714257, 2021). "While the mechanism underlying linc-OIP5 regulated angiogenesis with abrogating direct apposition is not yet fully understood, it might be a probable way to facilitate the interaction between the signaling networks in cancer cells and angiogenesis in ECs at a tumor microenvironment." (PMID 32046779, 2020). "We have excluded the least cancer-associated CTA genes: Magea12, Magea9b, Oip5 and Casc5." (PMID 41009820, 2025). "Notably, OIP5.AS1 is recognized for its oncogenic role in various cancers and its involvement in cellular proliferation." (PMID 38326441, 2024). "A recent pan-cancer study showed that overexpressed OIP5 (Mis18β) may contribute to tumor progression by increasing genome instability and affecting the tumor microenvironment." (PMID 39135477, 2024). "We first evaluated the expression of OIP5 in pan-cancer data from TCGA and GTEx." (PMID 37660035, 2023). "OIP5 is one of the ideal targets for tumour immunotherapy, and the amount of its expression determines the expression of apoptosis-related genes, which affects cancer progression." (PMID 36175893, 2022). "Recently, OIP5 has also been reported to be upregulated in the tumors of colorectal cancer patients and in female acute myeloid leukemia patients, implicating the protein as a potential therapeutic target for cancer." (PMID 28184024, 2017). "Previous reports demonstrated the abundance of Oip5 in cancer cells." (PMID 24516558, 2014). "Furthermore, the relationship between OIP5 and cancer immunity remains uncertain." (PMID 35242130, 2022).
cancer (continued). "It has been demonstrated that OIP5 may contribute to the growth of cancer." (PMID 24516558, 2014). "Compared to these efforts, our study uniquely focuses on the cancer-testis antigens DKKL1, FBXO39, and OIP5, which have been largely underexplored in CRC immunotherapy despite their selective overexpression and potent immunogenic potential." (PMID 40599850, 2025). "Of note, 6 CTA genes CEP55, KIF2C, TTK, OIP5, CASC5, and NUF2 had higher expression levels in the higher-TMB subtype of at least 15 cancer types, while had higher expression levels in the lower-TMB subtype of at most 3 cancer types." (PMID 30634925, 2019). "Markedly, the CTA genes ATAD2, CEP55, FANCA, KIF2C, NUF2, OIP5, and PBK had significantly positive expression correlations with the PLK1 expression in 30 cancer types (Pearson correlation, FDR<0.1)." (PMID 30631355, 2018). "What is most important and a new observation from our studies, a similar correlation was found between expression of OIP5 in CRC and advanced stages of this cancer." (PMID 27635108, 2016). "Six genes (SLCO2A1, MGAT4B, SLC25A33, MCCC1, OIP5, and CTHRC1) have been shown to affect the tumorigenesis of other cancer types but not PC." (PMID 30024105, 2018).
tumor (20 papers, 2015 to 2025). "OIP5 expression also positively correlates with tumor mutational burden and microsatellite instability in several cancers." (PMID 38596293, 2024). "When we integrated several of these genes into a multivariate LASSO regression model to define poor tumour outcome in the BX‐Neu+ mouse cohort, four genes were identified that were associated with poor survival in BX‐Neu+ mice: Oip5, Higd1a, Shc4 and Scrg1." (PMID 38344872, 2024). "Consistent with its associations with adverse tumor features, OIP5 expression robustly stratifies pRCC tumors into a high- and low-risk group based on overall survival possibility." (PMID 34503297, 2021). "The presence of OIP5 in SigMuc1NW suggests the protein as a tumor‐associated antigen (TAA) in PC." (PMID 30024105, 2018). "The pretreatment tumor tissue lncRNAs OIP5, CCAT1, UCA1, and MALAT1 were overexpressed (value more than 1) in 69.29%, 70.73%, 31.70%, and 36.58% samples, respectively, as compared to the control value (value =1) derived from normal mucosal samples of patients." (PMID 40568293, 2025). "OIP5 contributes to genomic instability and tumor growth, making it a potential target for vaccine development." (PMID 40599850, 2025). "Among these CTAs: DKKL1, FBXO39, and OIP5 have emerged as particularly attractive targets for immunotherapy due to their specific overexpression in tumor tissues and roles in promoting oncogenesis." (PMID 40599850, 2025). "In general, this study revealed an important relationship between OIP5 gene and tumor immune microenvironments." (PMID 35242130, 2022). "It was found that OIP5 silencing in nude-mouse tumor tissues not only slowed tumor growth and reduced size, but also significantly downregulated the expression of fatty acid pathway-related genes (ACSL1, ACSL2, and HADH)." (PMID 36661650, 2022). "High expression of OIP5 gene correlated significantly with the patient’s age (P =0.026), the tumor histological grade (P <0.001), T classification (P <0.001), N classification (P <0.001), M classification (P <0.001) and clinical stage (P <0.001)." (PMID 35242130, 2022). "We found that the silenced-OIP5 gene group (sh-OIP5) grew slower, smaller, and had a lighter tumor weight compared to normal controls, and the exogenous restoration of OIP5 expression significantly reversed these phenomena." (PMID 36661650, 2022). "Overall, these figures indicate that linc-OIP5 knockdown in MDA-MB-231 cells suppresses the HUVECs capillary-like tube formation at a tumor microenvironment." (PMID 32046779, 2020). "We initially proposed that OIP5 expression itself can activate the AKT/mTORC1 pathway, which prominently contributes to tumor cell proliferation in association with G1/S cell cycle progression and, to a lesser extent, tumor metastasis." (PMID 28184024, 2017). "Cells with knockdown of OIP5 via target shRNA exhibited reduced hepatic mass formation and metastatic tumor nodules in an orthotopic mouse model." (PMID 28184024, 2017). "To examine the role of these pathways in tumor cell growth and metastatic ability, we measured cell growth in OIP5-expressing HLK3 cells treated with the mTORC1 inhibitor rapamycin (RPM, 100 nM) or the β-catenin inhibitor cardamonin (CDM, 10 μM)." (PMID 28184024, 2017). "miR-15b-5p was inversely regulated in a cyclic manner compared with OIP5 mRNA levels, and plays a role in the inhibition of oncogenic signaling of OIP5 through targeting mTORC1 and β-catenin, as well as functioning as a tumor suppressor." (PMID 28184024, 2017). "The schematic model demonstrated that OIP5 regulates tumor growth and metastasis through AKT activation, which is mediated by both mTORC2 activation and p38/PTEN inactivation." (PMID 28184024, 2017). "RPM substantially inhibited OIP5-dependent tumor cell growth, but had a smaller effect on OIP5-independent tumor cell growth." (PMID 28184024, 2017).